NFKB2 (nuclear factor kappa B subunit 2)
Description:
NF-kappa-B is a pleiotropic transcription factor present in almost all cell types and is the endpoint of a series of signal transduction events that are initiated by a vast array of stimuli related to many biological processes such as inflammation, immunity, differentiation, cell growth, tumorigenesis and apoptosis. NF-kappa-B is a homo- or heterodimeric complex formed by the Rel-like domain-containing proteins RELA/p65, RELB, NFKB1/p105, NFKB1/p50, REL and NFKB2/p52. The dimers bind at kappa-B sites in the DNA of their target genes and the individual dimers have distinct preferences for different kappa-B sites that they can bind with distinguishable affinity and specificity. Different dimer combinations act as transcriptional activators or repressors, respectively. NF-kappa-B is controlled by various mechanisms of post-translational modification and subcellular compartmentalization as well as by interactions with other cofactors or corepressors. NF-kappa-B complexes are held in the cytoplasm in an inactive state complexed with members of the NF-kappa-B inhibitor (I-kappa-B) family. In a conventional activation pathway, I-kappa-B is phosphorylated by I-kappa-B kinases (IKKs) in response to different activators, subsequently degraded thus liberating the active NF-kappa-B complex which translocates to the nucleus. In a non-canonical activation pathway, the MAP3K14-activated CHUK/IKKA homodimer phosphorylates NFKB2/p100 associated with RelB, inducing its proteolytic processing to NFKB2/p52 and the formation of NF-kappa-B RelB-p52 complexes. The NF-kappa-B heterodimeric RelB-p52 complex is a transcriptional activator. The NF-kappa-B p52-p52 homodimer is a transcriptional repressor. NFKB2 appears to have dual functions such as cytoplasmic retention of attached NF-kappa-B proteins by p100 and generation of p52 by a cotranslational processing. The proteasome-mediated process ensures the production of both p52 and p100 and preserves their independent function. p52 binds to the kappa-B consensus sequence 5'-GGRNNYYCC-3', located in the enhancer region of genes involved in immune response and acute phase reactions. p52 and p100 are respectively the minor and major form; the processing of p100 being relatively poor. Isoform p49 is a subunit of the NF-kappa-B protein complex, which stimulates the HIV enhancer in synergy with p65. In concert with RELB, regulates the circadian clock by repressing the transcriptional activator activity of the CLOCK-BMAL1 heterodimer.
Synonyms: Lyt10; LYT-10; p52; p105; NF-kB2; p49/p100; CVID10; H2TF1; p100
Tractability: Small molecule: a drug acting on it is in phase 2 or 3 trials; a high-quality ligand is known; it has a binding pocket of medium quality. PROTAC: UniProt records ubiquitination sites on it; ubiquitination databases record sites on it; its protein half-life has been measured; a small molecule that binds it is known.
Target class: Other cytosolic protein
Gene: Protein-coding gene on chromosome 10 (102,394,110 to 102,402,529, forward strand). Ensembl gene ENSG00000077150.
Subcellular location: Nucleus; Cytoplasm
Subcellular location (Human Protein Atlas): Cytosol; Nucleoplasm
Pathways (Reactome):
Immune System: DEx/H-box helicases activate type I IFN and inflammatory cytokines production; Dectin-1 mediated noncanonical NF-kB signaling; Interleukin-1 processing; NIK-->noncanonical NF-kB signaling; RIP-mediated NFkB activation via ZBP1; Regulation of PD-L1(CD274) transcription; TAK1-dependent IKK and NF-kappa-B activation; TRAF6 mediated NF-kB activation; The NLRP3 inflammasome
Disease: IkBA variant leads to EDA-ID; Purinergic signaling in leishmaniasis infection
Chromatin organization: PKMTs methylate histone lysines
Metabolism of proteins: SUMOylation of immune response proteins
Gene Ontology:
Molecular function: DNA-binding transcription activator activity, RNA polymerase II-specific; protein binding; RNA polymerase II cis-regulatory region sequence-specific DNA binding; sequence-specific double-stranded DNA binding; DNA-binding transcription factor activity; DNA-binding transcription factor activity, RNA polymerase II-specific; DNA binding
Biological process: canonical NF-kappaB signal transduction; positive regulation of transcription by RNA polymerase II; regulation of DNA-templated transcription; intracellular signaling cassette; non-canonical NF-kappaB signal transduction; response to cytokine; response to lipopolysaccharide; signal transduction
Cellular component: Bcl3/NF-kappaB2 complex; cytoplasm; cytosol; nucleoplasm; nucleus; chromatin; I-kappaB/NF-kappaB complex
Genetic constraint (gnomAD): Loss-of-function variants: 21 observed, 98.12 expected, observed/expected ratio (o/e) 0.21, 90% interval 0.15 to 0.31. The upper end of that interval is the gene's LOEUF score, 0.31, which puts it in group 1 of 6, group 1 being the genes least tolerant of losing a copy. Missense variants: 806 observed, 1,137.1 expected, observed/expected ratio (o/e) 0.71, 90% interval 0.67 to 0.75. Synonymous variants: 478 observed, 470.28 expected, observed/expected ratio (o/e) 1.02, 90% interval 0.94 to 1.1.
Gene-disease validity (ClinGen):
ClinGen rates the evidence that NFKB2 causes each of these diseases.
immunodeficiency, common variable, 10 (autosomal dominant): Definitive. Any common variable immunodeficiency in which the cause of the disease is a mutation in the NFKB2 gene.
Homologues: Orthologues: chimpanzee NFKB2 (99% identical), macaque NFKB2 (98% identical), pig NFKB2 (93% identical), dog NFKB2 (93% identical), mouse Nfkb2 (92% identical), rat Nfkb2 (90% identical), guinea pig NFKB2 (84% identical), rabbit NFKB2 (71% identical), tropical clawed frog nfkb2 (56% identical), Drosophila melanogaster dl (24% identical), Drosophila melanogaster Dif (21% identical). Paralogues in human: NFKB1 (43% identical), RELA (18% identical), RELB (18% identical), REL (17% identical).
Diseases named in the same sentence as NFKB2 in open-access papers:
NFKB2 is named in the same sentence as 163 diseases in open-access papers, as found by Europe PMC text mining. Sharing a sentence is not in itself a finding about the gene and the disease. The quoted sentences say what the papers report.
common variable immunodeficiency (15 papers, 2015 to 2023). "Heterozygous mutations in NFKB2 have recently been established as a molecular cause of common variable immunodeficiency (CVID) and DAVID-syndrome, a rare condition combining deficiency of anterior pituitary hormone with CVID." (PMID 30941118, 2019). "Heterozygous C-terminal mutations in NFKB2 have been associated with early-onset common variable immunodeficiency (CVID), central adrenal insufficiency and ectodermal dysplasia." (PMID 31417880, 2019). "Single reports suggest an increased risk of severe COVID19 in patients with NFKB2 deficiency and reports including a large number of patients with common variable immunodeficiency (CVID) suggested a higher fatality rate from SARS-CoV-2 infections among a subgroup." (PMID 34893946, 2022). "NFKB2 was first reported as the gene responsible for autosomal dominant (AD) common variable immunodeficiency (CVID) (OMIM: 615577), and this discovery was followed by NFKB1 as another gene responsible for AD-CVID." (PMID 33499153, 2021).
breast carcinoma (10 papers, 2015 to 2025). "We also identified 71 genes bound by NFKB2 that were upregulated with low DAB2IP in both the ChIP-Seq and TCGA RNA-Seq datasets, which were enriched in terms associated with breast cancer." (PMID 39418101, 2024). "For example, IRF1 could inhibit NFKB2 activity to induce breast cancer cell-specific growth inhibition." (PMID 34445498, 2021). "However, since the critical upstream kinase NIK, has not been found to be widely stabilized in breast cancer cells, more work needs to be done to uncover the mechanisms by which RelB and NFKB2 expression and activity are promoted in breast cancers." (PMID 29874793, 2018). "NFKB2 was involved in MAPK, NF‐kappa B, and breast cancer pathways, and played a critical role in mammary gland development." (PMID 40590069, 2025). "We determined the effect of NF-κB activation in DAB2IP-low Luminal A breast cancer by profiling RELA, RELB, and NFKB2 genomic binding and gene expression using ChIP-Seq in stable DAB2IP knockdown and control T47D cells." (PMID 39418101, 2024). "RELA, RELB, CREL, NFKB1 and NFKB2, and the upstream regulators NEMO and NIK were knocked-down in lymph endothelial cells (LECs) and in MDA-MB231 breast cancer spheroids to study the contribution of NF-κB in vascular barrier breaching." (PMID 26513020, 2015). "Overall, the role of non-canonical NFkB2 in breast cancer pathogenesis is under-studied." (PMID 32708944, 2020). "Non-canonical NFkB2 signaling creates a slow, sustained activation of the pathway compared to rapid canonical signaling, but it has also been shown that p100 can sequester the canonical p50/p65 heterodimer in the cytoplasm in breast cancer." (PMID 32708944, 2020).
COVID-19 (10 papers, 2020 to 2023). A disease caused by infection with severe acute respiratory syndrome coronavirus 2. "NF-kB signaling pathway genes (NFKBIA, NFKB1, RELA, NFKB2) were up-regulated in COVID-19 patients." (PMID 36380355, 2022). "In addition, we found that many immune-related signaling pathways (Fc-epsilon, NF-κB/NFKB2, and C-type lectin receptor) could be activated in the lungs of COVID-19 patients." (PMID 33060566, 2020). "Upregulated genes in early COVID-19 mortality included many involved with interferon signaling (e.g., GBP2, ISG15), the NF-κB pathway (e.g., NFKB2, NFKBIA), and TNF-α and IL-1 signaling (e.g., TANK, NOD1, RELA)." (PMID 35446789, 2022). "Genes that were found to be upregulated in the early COVID-19 mortality cases and involved with the interferon (ISG20, IRF1, GBP2) and NF-κB (NFKB2, NFKBIA, TNFAIP3) pathways showed linear decline with longer symptomatic interval." (PMID 35446789, 2022). "In the COVID-19 cohort, IL6, PTSG2, JUN, ATF3, SOCS3, CSF3, and NFKB2 had AUC values greater than 0.7." (PMID 36380355, 2022). "NFKB1, NFKB2, IRF1, and CXCR3 were specifically up-regulated in COVID-19, and CXCL10, STAT1, TLR4, and genes for class II HLA and immunoproteasome subunits were specifically up-regulated in influenza." (PMID 32651212, 2020). "When we directly compared COVID-19 and influenza, NFKB1, NFKB2, and TNF were up-regulated in COVID-19, whereas STAT1, TLR4, and genes for immunoproteasome subunits were up-regulated in influenza." (PMID 32651212, 2020). "Among our results, several immune-related pathways including those activated by Fc-epsilon-related signaling (LYN and PI3K), NIK/NF-κB (ub, CUL1, SKP1, proteasome, and NFKB2), and via C-type lectin receptor pathways (PTPN11 and CARD9) were enriched in the COVID-19 lungs." (PMID 33060566, 2020). "We identified upregulation of several NFκB pathway components (NFKB2 and NFKBIA) and inflammatory cytokines (CXCL9, CCL17, and CCL21) in the presence of viral transcripts, in line with the abundant literature describing these molecules in the early steps of COVID-19 pathogenesis." (PMID 37858234, 2023).
antibody deficiency (9 papers, 2019 to 2023). "Typical clinical features of NFKB2 deficiency are early onset hypogammaglobulinemia, recurrent respiratory infections, poor Ab responses to vaccines, autoimmunity, and adrenocorticotropic deficiency." (PMID 37273190, 2023). "Heterozygous pathogenic variants in NFKB1 and NFKB2, the genes encoding the central components of the canonical and non-canonical NF-κB signaling pathways, have both been associated with primary antibody deficiencies." (PMID 33995346, 2021). "In contrast, heterozygous damaging mutations in NFKB2 represent a distinct, early-onset entity, exceeding the usual clinical spectrum of antibody deficiency, and affecting diverse lymphocyte subpopulations." (PMID 33995346, 2021). "Thus, occurrence of immunodeficiency, mainly in terms of respiratory infections typical for antibody deficiency, was the major presentation of NFKB2-mutated patients before pituitary dysfunction became apparent in the further course of disease." (PMID 30941118, 2019). "The most frequent main genetic causes of predominantly antibody deficiencies in children infected with SARS-CoV-2 were BTK (n = 41), NFKB2 (n = 4), TNFRSF13B (n = 3), PIK3CD (n = 3), and PIK3R1 (n = 2)." (PMID 37559153, 2023). "For instance, mutations in TNFRSF13B, NFKB1, NFKB2, CTLA4 and STAT3 are indications for the early molecular diagnosis of patients with predominantly antibody deficiency such as predominantly antibody deficiencies." (PMID 37033178, 2023). "A number of previous studies have outlined the clinical phenotypes of large patient groups with antibody deficiency who have mutations in selected genes, including the TACI gene, CTLA4, NFKB1, NFKB2, STAT3, PI3KCD, or LRBA." (PMID 38274105, 2023). "Many patients affected by NFKB2 mutations demonstrated a severe clinical course, which is not typical for isolated antibody deficiency." (PMID 30941118, 2019). "Within the IEI classified as predominant antibody deficiency, we detected specific IgG+ RBD+ MBCs in half of them, with the exception of 1 patient with CVID, 1 patient with NFKB1 deficiency, 1 patient with NFKB2 deficiency, and 1 patient with suspected IEI without confirmed genetic diagnosis." (PMID 37215146, 2023).
Autoimmunity (9 papers, 2019 to 2025). The occurrence of an immune reaction against the organism's own cells or tissues. "Almost all NFKB2 mutations described to date in patients with autoimmunity are missense and frameshift mutations located in exons 22 and 23 and affect the C-terminal portion of the protein that is responsible for regulating p100 processing." (PMID 36733767, 2022). "Early-onset PID and a variable degree of autoimmunity became evident in the vast majority of individuals with mutations in NFKB2." (PMID 30941118, 2019). "Moreover, in humans, rare mutations in NFKB2 cause an autosomal dominant human syndrome of hypogammaglobulinemia and increased susceptibility to infections, often accompanied by organ-specific autoimmunity." (PMID 36555871, 2022). "Clinical features, neurology, endocrinology, and autoimmunity in patients with NFKB2 mutations." (PMID 30941118, 2019). "NF-κB2 and RelB are important regulators of immune tolerance, as shown by germline deletion of the respective proteins in Relb−/− and Nfkb2−/− mice, which results in spontaneous autoimmunity." (PMID 35672519, 2022). "Global Bcl3 knockout mice also do not show signs of autoimmunity, whereas the combined absence of Bcl3 and Nfkb2 results in the loss of central tolerance and autoimmunity." (PMID 40359334, 2025). "Young mice with a Treg cell–specific inactivation of Nfkb2 did not display abnormal inflammation or autoimmunity." (PMID 35672519, 2022).
immune deficiency (9 papers, 2014 to 2025). "A relevant example of a complex immune deficiency co-occurring with endocrinopathy is a variant in NFKB2 (p52LOF/IκBδ GOF)." (PMID 40141295, 2025). "Deficient Anterior pituitary with common Variable Immune Deficiency (DAVID) syndrome results from NFKB2 heterozygous mutations, causing adrenocorticotropic hormone deficiency (ACTHD) and primary hypogammaglobulinemia." (PMID 39607428, 2024). "Mutation of NFKB2 (nuclear factor kappa B subunit 2) is associated with immunodeficiency, including the CD4+ or CD8+ T cell dysfunction but normal function and number of NK cells." (PMID 35341155, 2022). "Of note, activating mutations have been recently identified in NFKB2, which lead to immunodeficiency in a different manner." (PMID 36289712, 2022). "This suggests that B cell function and differentiation, rather than their absolute number, play essential roles in pathogenesis of immunodeficiency in patients with NFKB2 mutations." (PMID 30941118, 2019). "We confirm previous findings that mutations near the C-terminus of NFKB2 cause combined endocrine and immunodeficiencies." (PMID 25524009, 2014). "Given the clinical phenotype of ACTH deficiency and features of a B cell defect, deficit in anterior pituitary function with variable immune deficiency (DAVID) syndrome secondary to damaging variant(s) in candidate genes including NFKB2, TNFRSF138, IKZF1 and TBX19 was suspected." (PMID 36494638, 2022). "Most patients were diagnosed with CVID (10/16 patients, one of whom due to NFKB2 deficiency), four patients with X-linked agammaglobulinemia (XLA), one patient with immunodeficiency due to Kabuki syndrome and one with Hyper-IgM syndrome of unknown origin." (PMID 34893946, 2022). "Absence of primary immune deficiency and autoimmunity in some individuals is consistent with variable clinical expressivity of loss of function mutations in the NFKB2 gene." (PMID 36494638, 2022). "Indeed, while concomitant common variable immune deficiency (CVID) can be explained by the key roles of NFKB signaling in the immune system, the mechanism of the endocrine deficits caused by NFKB2 mutants was unknown." (PMID 39607428, 2024). "The phenotype observed upon conditionally deleting Nfkb2 in murine GC B cells, specifically the absence of long-lived plasma cells, suggests that B-cell autonomous components contribute to the immune deficiency that results from defective lymphoid organ development." (PMID 36289712, 2022).
myeloma (7 papers, 2008 to 2024). "Recently, genetic alterations in components of the noncanonical and canonical NF-κB pathways (e.g., NIK, TRAF3, CYLD, BIRC2/BIRC3, CD40, NFKB1, or NFKB2) resulting in their activation have been identified in multiple myeloma." (PMID 18596915, 2008). "MMCLs were treated with different concentrations of inhibitors or control compound for 16 h, and then NFkB activity was measured by determining the RNA expression levels of 3 NFkB target genes - cIAP2, TNFAIP3, NFKB2, which are the most sensitive target genes in myeloma cells." (PMID 24980832, 2014). "Given the significant role of super-enhancers (SEs) in regulating myeloma transcriptomes and the ability of NF-κB to coordinate SE formation, we analysed the SE profiles based on H3K27 acetylation in NFKB2 KD KMS-11 cells and primary MM tumours." (PMID 38514625, 2024). "Targeting the non-canonical NF-κB pathway through NFKB2 knockdown resulted in the disruption of oncogenic transcriptional programmes shared with myeloma patients displaying high NF-κB activity (NF-κB+), along with the activity of p52-responsive enhancers." (PMID 38514625, 2024).
viral infection (7 papers, 2013 to 2025). "Among the increased transcription factor IRFs, STATs, MYC, NFKB1, NFKB2, and NF-kappa B RELA have been implicated in viral infection." (PMID 34940755, 2021). "Besides, genetic defects in some molecules that interact with T cells (such as NFKB1, NFKB2, and TNFRSF13B) in patients diagnosed with CVID can also lead to critical viral diseases." (PMID 40442532, 2025).